KLF4 (KLF transcription factor 4)
Diseases named in the same sentence as KLF4 in open-access papers (continued):
Sharing a sentence is not in itself a finding about the gene and the disease.
breast cancer (continued). "Positive controls were human seminoma for OCT4 (pink, arrows), normal skin for SOX2 (pink, arrows), seminoma for NANOG (pink, arrows), breast cancer for KLF4 (pink, arrows), and normal prostate for c-Myc (pink, arrows)." (PMID 29404335, 2017). "On the other hand, expression of Nanog, Bmi1, and Klf4 was inversely correlated with aggressive features of the breast cancers." (PMID 28422735, 2017). "Normal positive staining patterns for OCT4 (brown), NANOG (purple), SOX2 (brown), c-Myc (brown), and KLF4 (purple) were demonstrated on human seminoma, normal skin, breast cancer, and prostate tissues, respectively." (PMID 29404335, 2017). "On the other hand, expression of Nanog, Bmi1, and Klf4 was inversely correlated with aggressive features of the breast cancer." (PMID 28422735, 2017). "On the other hand, it was reported that KLF4 acts as an oncogene in primary breast cancer and oral and dermal squamous cell carcinoma cells." (PMID 28380435, 2017). "Klf4 inhibited the transcriptional activity of ER-α and so suppressed estrogen-dependent breast cancer cell growth." (PMID 28422735, 2017). "MicroRNA-206 in mammary cancer stem-like cells (McCSCs) mediates Zinc-finger transcription factor Kruppel-like factor 4 (KLF4) pro-survival signaling through repression of the pro-apoptotic molecules programmed cell death 4 (PDCD4) and Cx43." (PMID 27229305, 2016). "KLF4 is considered to be critical for the maintenance of breast cancer stem cells and to induce cancer development." (PMID 27612430, 2016). "In the current study, we analyzed the expression and function of the main KLF4 isoform, KLF4α, in breast cancer cells." (PMID 27323810, 2016). "We have established that KLF4α is expressed in the cytoplasm of breast cancer cells and present evidence that an increased KLF4α/KLF4(FL) ratio is often found in tumors compared to normal tissue." (PMID 27323810, 2016). "In breast cancer, KLF4 inhibits epithelial-to-mesenchymal transition through regulation of E-cadherin gene expression." (PMID 27302923, 2016). "High E-Cadherin, p21Cip1, and p27Kip1 levels mostly correlated with high expression of KLF4(FL) in the breast cancer cell lines." (PMID 27323810, 2016). "Krüppel-like factor 4 (KLF4) overexpression increased PFKP expression as well as glycolytic activity in breast cancer cell lines." (PMID 27049827, 2016). "To study KLF4(FL) and KLF4α function in breast cancer cells, we cloned both cDNAs into mammalian expression plasmids and transfected MDA-MB-231 cells." (PMID 27323810, 2016). "MiR-7 down-regulates expression of KLF4 in breast cancer stem cells and suppresses EGFR mRNA in several cancers by binding to sites in its 3′-UTR." (PMID 26840086, 2016). "Our data suggest that KLF4α acts as a dominant KLF4(FL) antagonist and prevents nuclear translocation of KLF4(FL), thereby altering the transcriptional landscape in breast cancer cells." (PMID 27323810, 2016). "Here we report that exposure of breast cancer cells to hypoxia also induces ZNF217-dependent inhibition of m6A methylation of mRNAs encoding NANOG and KLF4, which is another pluripotency factor that mediates BCSC specification." (PMID 27590511, 2016). "Consistent with previous investigations of odontoblasts, NFI-C also induced MET in breast cancer cells via upregulation of KLF4 and E-cadherin and down-regulation of Slug, a dominant regulator of EMT initiation." (PMID 25879941, 2015). "Transient adenoviral expression of KLF4 in the 4T1 orthotopic mammary cancer model significantly attenuated primary tumor growth as well as micrometastases to the lungs and liver." (PMID 26110566, 2015). "For example, KLF4-transformed rat kidney epithelial cells produce tumors in mouse xenografts, and KLF4 expression is increased in ductal carcinoma of the breast cancer cells, in dermal squamous cell carcinomas, and in head and neck squamous cell carcinomas." (PMID 26517087, 2015).
breast cancer (continued). "In line with this notion, it has been reported that overexpression of KLF4 in breast cancer cells led to an increase of the cancer stem cell-like population." (PMID 26109433, 2015). "To validate the oncogenic role of arginine methylation of KLF4 in breast cancer, we further conducted an in vivo mouse xenograft study." (PMID 26420673, 2015). "Klf4 is required for maintaining stem-like properties and for cell migration and invasion in breast cancer." (PMID 26462028, 2015). "This is reasonably supported by the upregulation of KLF4 in breast cancer stem cells as defined by marker expression, and the observed loss in bulky cancerous tissues." (PMID 24429391, 2014). "In the present study, we analyzed the expression profiles of the same panel of stemness genes belonging to the OCT3/SOX2/NANOG/KLF4 core circuitry and acting in regulating stem cell biologyin a representative sample of primary breast cancer tissue." (PMID 25127259, 2014). "In sharp contrast, KLF4 acts as an oncogene in a breast cancer context where elevated KLF4 expression has been observed." (PMID 25181544, 2014). "Altogether, the most recent reports point towards KLF4 as a tumor suppressor, being downregulated in human breast cancer samples." (PMID 25593984, 2014). "KLF4 belongs to zinc finger family of transcription factors, which has been reported to be critical for the maintenance of breast cancer stem cells and their aggressive behavior such as migration and invasion ad resistance to cisplatin." (PMID 25216266, 2014). "To compare the actions of KLF4 in MCF7 breast cancer with that in ovarian cancer cells, we performed similar experiments using the same lentiviral Tet-on inducible vector-transduced in MCF7 cells." (PMID 25137052, 2014). "Alternatively, KLF4 transcription was essential in the maintenance of a breast cancer stem cell (CSC) population." (PMID 24429391, 2014). "Our analysis of the Uppsala database of breast cancer revealed that low Klf4 expression correlated with shorter disease-free survival." (PMID 23451207, 2013). "Upregulation of KLF4 in the breast and the skin leads to breast cancer and squamous cell carcinoma, respectively." (PMID 23861801, 2013). "Klf4 expression was also found reduced in human breast cancer cell lines, such as in SKBR3 upon EGF-induced EMT and in MCF7 cells which undergo EMT upon stable depletion of E-cadherin." (PMID 23451207, 2013). "The acceleration of EMT upon depletion of Klf4 function was further confirmed in Py2T murine breast cancer cells." (PMID 23451207, 2013). "Decreased expression of Klf4 during TGFβ-induced EMT was also confirmed in the murine breast cancer cell line Py2T, which has been established from a breast tumor of MMTV-PyMT transgenic mice, as well as in EpRas cells." (PMID 23451207, 2013). "The capacity of self-renewal is pivotal for CSCs maintaining and for cancer recurrence KLF4 is essential to maintain the characteristic of CSCs and required for the capacity to migrate and invade in breast cancer." (PMID 23418515, 2013). "Yet, Klf4 has also been found highly expressed in dysplastic epithelium, in breast cancers and in squamous cell carcinoma of the oropharynx." (PMID 23451207, 2013). "On the other hand, high level and oncogenic role of KLF4 were also reported in human breast cancer and oral squamous carcinoma." (PMID 21978458, 2011). "The oncogenic properties of KLF4 in breast cancers was also confirmed in vitro and using xenograft tumor model in which KLF4 knockdown inhibited breast cancer development." (PMID 21978458, 2011). "Immunohistochemistry was employed to investigate the expression of KLF4 in 142 cases of canine mammary tumor." (PMID 21978458, 2011). "In this study, we investigated the expression and clinical relevance of KLF4 in canine mammary carcinoma." (PMID 21978458, 2011). "The present study examined the expression of KLF4 and assessed its significance in canine mammary carcinoma." (PMID 21978458, 2011).
breast cancer (continued). "Immunihistochemistry revealed that nuclear expression of KLF4 was elevated in tumor cells of canine mammary carcinoma." (PMID 21978458, 2011). "Analyzing the expression of KLF4 in paraffin-embedded tissues by IHC revealed up-regulated nuclear KLF4 expression in mammary carcinomas as compared to benign tumor cases." (PMID 21978458, 2011). "We provided evidence for the first time that KLF4 is preferentially and highly expressed in canine mammary carcinoma." (PMID 21978458, 2011). "For instance, in vitro experiments using Estrogen receptor (ER) α positive breast cancer cell line MCF7 have revealed that estrogen dependent cell-growth was significantly enhanced by knockdown of Klf4." (PMID 20514221, 2009). "Altered expression of Atp1b1, CARD 10, KLF4, Spint2, and Acly in AA breast cancer cells was observed when the overall averages of the expression levels of all AA and CAU cancer cell lines were compared." (PMID 17472751, 2007). "In breast cancer, the lack of strong pro‐inflammatory pathogenic stimulation renders KLF4 more likely to support tumor immune‐escape pathways." (PMID 41532367, 2026). "This suggests that KLF4 contributes to breast cancer tumorigenesis by regulating MDSC function." (PMID 40552304, 2025). "Furthermore, correlation analysis unveiled a positive correlation between ANGPTL4 and KLF4 expression in breast cancer specimens." (PMID 40616161, 2025). "Furthermore, we validated ANGPTL4 and KLF4 protein expression in breast cancer patients using immunohistochemistry (IHC) on a tissue microarray comprising of 58 breast cancer samples and 49 adjacent normal breast tissues." (PMID 40616161, 2025). "Similarly, the overexpression of KLF4 in breast cancer CSCs is correlated with an aggressive phenotype." (PMID 39547513, 2024). "Ataxin-3 deubiquitinates KLF4, stabilising the protein, and promoting breast cancer metastasis." (PMID 38497605, 2024). "Subsequently, exosomal miR-10b could be taken up by different TNBC cells and suppress the protein levels of its target genes, such as HOXD10 and KLF4, thereby promoting breast cancer cell invasion." (PMID 38124743, 2023). "KLF4 acted as a tumor suppressor in gastrointestinal tumors and cutaneous squamous cell carcinoma, and as a pro-cancer factor in cutaneous melanoma and breast cancer." (PMID 37031197, 2023). "Hypoxia, through hypoxia-inducible factor (HIF), is known to induce a human Embryonic SC (hESC)-like transcriptional program, including the induced pluripotent stem cell (iPSC) inducers OCT4, NANOG, SOX2, KLF4, and cMYC, in various cancer cell lines, including breast cancer." (PMID 36982940, 2023). "However, in a few types of tumors, such as breast cancer and glioblastoma, KLF4 appears to be a “oncogene”." (PMID 37031197, 2023). "By modifying KLF4, miR-7 prevented breast cancer stem-like cells from metastasizing to the brain." (PMID 37508580, 2023). "In melanoma and canine mammary tumors, Klf4 promotes tumorigenesis." (PMID 38164743, 2023). "They found that in breast cancer, KLF4 could upregulate the expression of PFKP by directly binding to the PFKP promoter." (PMID 37833332, 2023). "Additionally, miR-7-5p has demonstrated its ability to impede brain metastasis in breast cancer stem-like cells, achieved through the regulation of KLF4 expression." (PMID 38003971, 2023). "Since four RUNX1 binding sites were identified in the KLF4 promoter in a human leukemia cell model and KLF4 has been determined as an AR gene target in breast cancer cell lines, more experiments are needed to define the principal source of KLF4 gene expression activation." (PMID 36766786, 2023). "ATXN3 promotes breast cancer metastasis by stabilizing KLF4 through deubiquitination." (PMID 37349820, 2023). "KLF4 can promote the abilities of invasion and self-renewal of CSCs, which may serve as a therapeutic target for brain metastasis of breast cancer." (PMID 35958575, 2022).
breast cancer (continued). "FBXO32 suppresses breast cancer tumorigenesis by targeting KLF4 to proteasomal degradation." (PMID 35383144, 2022). "On the other hand, in stem-type breast cancer cell lines with metastatic capacity to the brain, a profile of miRNAs was made that showed a reduced expression of miR-7, which promotes the expression of KLF4 factor in induced pluripotent stem cells." (PMID 36012357, 2022). "However, in breast cancer, melanoma, and glioma, KLF4 was shown to promote cell growth and inhibit cell apoptosis." (PMID 36539799, 2022). "The transcription factor KLF4 has been shown to be a key regulator of macrophage polarization in models of both prostate and breast cancer, and is activated through STAT6 signaling; this, in turn, is triggered through IL-4 signaling and participates in limiting the pro-inflammatory response." (PMID 35359423, 2022). "In contrast, the oncogenic activity of KLF4 was discovered in breast cancer, where higher KLF4 expression was seen in primary breast ductal carcinoma compared to normal tissues; moreover, overexpression of KLF4 led to a poor prognosis in early-stage breast cancer." (PMID 35345512, 2022). "In addition, the inhibition of ZNF217-dependent m6A methylation of NANOG and KLF4 mRNA was found to be enhanced in breast cancer cells under hypoxia, thus promoting the occurrence and development of breast cancer." (PMID 35251177, 2022). "Additionally, some recent studies have shown that patients with higher KLF4 expression have better overall survival and disease-free survival rates in breast cancer and prostate cancer." (PMID 35177016, 2022). "Furthermore, after knockdown DNMT1 expression in MCF-7 and T47D breast cancer cells, the expression of KLF4 increased, and the sensitivity of breast cancer cells to PTX significantly increased." (PMID 34150611, 2021). "Mammospheres or breast cancer cells in hypoxia have higher expression of the KLF4, NANOG, OCT4, and SOX2 genes and CD44 and CD24, which encode pluripotency factors that are required for the maintenance of cancer stem cells, embryonic stem cells, and induced pluripotent stem cells." (PMID 34830821, 2021). "Furthermore, Polyphyllin III treatment induced the protective increase of xCT through KLF4 upregulation, which leads to the resistance of breast cancer cells to Polyphyllin III." (PMID 34040532, 2021). "LINC00115 forms an miR‐7/KLF4 pathway to promote breast cancer metastasis." (PMID 34697900, 2021). "Finally, 10 clinical specimens of breast cancer cases underwent immunohistochemical analysis of KLF4 and xCT." (PMID 34040532, 2021). "Breast cancer patients with high levels of KLF4 expression had relatively good RFS and OS rates." (PMID 33918002, 2021). "High KLF4 was shown to prevent metastasis in breast cancer and pancreatic cancer models." (PMID 34680284, 2021). "The results showed that the expression of KLF4 was decreased in breast cancer tissues." (PMID 34150611, 2021). "Therefore, a drug that can inhibit DNMT1 expression and promote the expression of KLF4 would considerably improve the status of PTX resistance in the clinical treatment of breast cancer." (PMID 34150611, 2021). "Furthermore, FBXO32 inhibited breast cancer oncogenesis and progression via interacting with KLF4 for its ubiquitination and degradation, a critical factor for cell fate decisions." (PMID 35046938, 2021). "KLF4 is a major target of demethylation drugs in enhancing the PTX sensitivity of breast cancer." (PMID 34150611, 2021). "We tested whether expression of either Klf4 or Sox2 was affected in BK5.ATF3 mammary tumors using RT-qPCR and found that both Klf4 and Sox2 were significantly upregulated (p < 0.005) in tumors with lower MiR145 levels." (PMID 33652981, 2021). "Additionally, ATXN3 was highly expressed in breast cancer and it promotes tumor tissue metastasis by deubiquitinating and stabilizing KLF4." (PMID 34482818, 2021). "It was found that the expression of KLF4 was different in the different breast cancer cells." (PMID 34150611, 2021).
breast cancer (continued). "In order to determine whether KLF4 mediates PTX sensitivity in breast cancer cells, the lentiviral vector containing KLF4 were used to overexpress KLF4 in MCF-7 and T47D breast cancer cells." (PMID 34150611, 2021). "However, the association of KLF4 expression, its functional alteration and PTX sensitivity in breast cancer are not well understood." (PMID 34150611, 2021). "In the 4T1 breast cancer mouse model, suppression of KLF4 expression significantly sensitizes breast cancer tumors to olaparib, clearly demonstrating the clinical relevance of KLF4 in synergizing PARP1 in anti‐TNBC breast cancer treatment." (PMID 33231937, 2020). "Collectively, our results demonstrate KLF4 could be a good clinical target in breast cancer treatment." (PMID 33231937, 2020). "ALKBH5 suppresses NANOG and KLF4 degradation, which promotes breast cancer progression." (PMID 32021563, 2020). "Our new findings highly suggest that KLF4 is a good target for breast cancer treatment." (PMID 33231937, 2020). "Furthermore, the co‐expression of KLF4 and PARP1 in breast cancer cell lines and breast cancer tissues was detected with accumulation of KLF4 PARylation." (PMID 33231937, 2020). "KLF4 anticancer activity in breast cancer is previously reported by several studies." (PMID 33490232, 2020). "In breast cancer, KLF4 can have both tumor suppressive and oncogenic functions." (PMID 32552913, 2020). "Moreover, low KLF4 expression is correlated with increased recurrence, and its expression is decreased in breast cancers compared to adjacent normal parenchyma." (PMID 32552913, 2020). "Therefore, our findings demonstrate a potential novel therapeutic strategy to target BRCA‐proficient TNBC breast cancer by exploiting the synergism of KLF4 and PARP1." (PMID 33231937, 2020). "However, additional studies are necessary to determine if KLF4 also directly regulates NRG1 expression in breast cancer." (PMID 32552913, 2020). "In addition, stronger interactions were seen between KLF4 and regions further upstream in the gene desert, which correlates with previous CHi-C findings in breast cancer cells and Hi-C findings in NHEK cells." (PMID 32366252, 2020). "In order to analyzing the correlation of the KLF4‐PARP1 axis with poor breast cancer prognosis, we have conducted additional immunohistochemistry measuring the expression levels of KLF4 and PARP1 based on an array of 117 human breast cancer tissue samples followed by Kaplan–Meier analysis." (PMID 33231937, 2020). "Alteration of KLF4 levels could be a good strategy to promote the efficacy of olaparib in killing breast cancer cells, especially for the population of TNBC patients who have normal BRCA1 function." (PMID 33231937, 2020). "However, KLF4 has also been reported to be a metastasis suppressor in breast cancer where it represses proliferation, migration, and invasion and promotes cell cycle arrest and apoptosis." (PMID 32552913, 2020). "In addition, we observed the elevation of KLF4 levels antagonizes killing efficacy for endocrine therapeutic agents as well as various chemotherapy agents in breast cancer treatment." (PMID 33231937, 2020). "Thus, abnormal accumulation of KLF4 and PARP1 protein levels in breast cancer tissues is associated with poor prognosis." (PMID 33231937, 2020). "Co‐localizations of both PARP1 and PAR with KLF4 were measured in breast cancer tissue specimens." (PMID 33231937, 2020). "To discover downstream protein targets of KLF4 in breast cancer, we examined the changes in protein expression and phosphorylation using a reverse phase protein array (RPPA) of extracts from MDA-MB-231 cells overexpressing KLF4 as a result of AdKLF4 infection compared to cells infected with AdGFP." (PMID 32552913, 2020).